PLIN5 (perilipin 5)
Diseases named in the same sentence as PLIN5 in open-access papers (continued):
Sharing a sentence is not in itself a finding about the gene and the disease.
sarcoma (1 paper, 2020). A usually aggressive malignant neoplasm of the soft tissue or bone. "PLIN2, PLIN3 and PLIN5 expressions were significantly different among non-lipomatous sarcoma (all P<0.01)." (PMID 32368290, 2020).
Sepsis (1 paper, 2026). Sepsis is defined as life-threatening organ dysfunction caused by a dysregulated host response to infection. "In the present study, we revealed that the KIF13B/PLIN5 axis serves as an important regulatory machinery in cardiac lipid homeostasis during sepsis." (PMID 41531892, 2026).
tumor (11 papers, 2019 to 2025). "Pathways associated with regulation of the tumor progression and microenvironment by exhibiting anti-inflammatory and anti-tumorigenic properties were more detected in Plin5-deficient animals." (PMID 39469452, 2024). "Whereas PLIN5 for the first time was shown to associate with HCC tumor in this study, the precise mechanism in which it is regulated during the onset or progression of HCC is still unknown." (PMID 30893876, 2019). "We determined mRNA expression profiles of PLIN1, PLIN2, PLIN3, PLIN4, and PLIN5 in a panel of OC cell lines and tumor tissue, using RT‐PCR." (PMID 41041279, 2025). "Itch-mediated ubiquitination of PLIN2/PLIN5 regulates LD protein turnover, influencing tumor metabolic adaptation." (PMID 40370434, 2025). "In the NAFLD-HCC model, the tumor area in the livers of WT mice was characterized by mixed vacuolated hepatocytes, while Plin5-/- mice only showed lipid accumulation." (PMID 38388533, 2024). "Considering that HCC development is highly driven by cytokines present in the tumor microenvironment, we decided to explore the possibility of PLIN5 being regulated by cytokines commonly known to contribute to NAFLD and HCC pathologies." (PMID 37108378, 2023). "Considering that HCC development is highly driven by cytokines present throughout NAFLD development and in the tumor microenvironment, we here explore the possible regulation of PLIN5 by cytokines known to be involved in HCC and NAFLD progression." (PMID 37108378, 2023). "And as one of the redox-dependent factors of tumor, PLIN5 indirectly affected the redox state of adipose tissue in GC, which was potentially related to the prognosis of patients with GC." (PMID 35223903, 2022). "The expression of PLIN5 launches in the tumor formation within HCC livers making it a promising marker for studies focusing on oncogenic effects in liver tissue." (PMID 30893876, 2019). "Furthermore, only wild-type (WT) mice treated with DMBA and WD developed liver tumors, while Plin5−/− mice were refractory to tumor development." (PMID 38388533, 2024). "Interestingly, many kinds of tumor samples showed lower PLIN5 expression compared to normal samples." (PMID 31614673, 2019). "The results demonstrated that the mRNA levels of PLIN1/PLIN4/PLIN5 were not correlated with tumor recurrence status, while PLIN2 and PLIN3 were correlated with tumor recurrence status." (PMID 37189627, 2023).
cancer (10 papers, 2016 to 2025). A tumor composed of atypical neoplastic, often pleomorphic cells that invade other tissues. "Additionally, ELP6 and PLIN5 mutations have been seldom studied in GC samples, but they were studied in some other cancers." (PMID 35223903, 2022). "We next analyzed the Western blot results of CGI-58, PLIN1, and PLIN5 according to cancer type (colorectal, n = 6; gastric, n = 5; pancreatic, n = 7) vs controls (n = 8)." (PMID 38167536, 2024). "It was only a few years ago that PLIN5 started to emerge as a potential prognostic biomarker or a treatable target in several types of cancer." (PMID 37108378, 2023). "This review discusses PLIN5 as a key regulator of pathways involved in pathogenesis of NAFLD and cancer." (PMID 34067931, 2021). "However, with LD accumulation in cancer cells, PLIN5 remains sequestered on the LD membrane, thereby allowing the unrestrained HSR to exert its cancer-promoting functions." (PMID 30111611, 2018). "They suggested that PLIN1, PLIN2, and PLIN3 may be involved in cancers such as hepatocellular adenoma and carcinoma, sebaceous adenoma and carcinoma, and lipoma tumors, while PLIN5 was excluded as not sufficient proof was given." (PMID 34067931, 2021).
metabolic disorders (6 papers, 2021 to 2025). "This systematic review attempts to delineate the metabolic disorders associated with pathological cardiac remodeling, focusing on the properties and regulatory mechanisms of Plin5." (PMID 40166465, 2025). "Our results indicate that Plin5 can alleviate the metabolic disorder caused by excessive FFA in the body." (PMID 34638947, 2021). "PLIN5-mediated reorganization of mitochondria-LD interactions highlights a key metabolic adaptation and suggests potential therapeutic strategies for metabolic disorders such as MASLD." (PMID 39803529, 2024). "Our results demonstrated that Plin5 plays a critical role in coordinating fatty acid and glucose oxidation in cardiomyocytes, providing a potential target for the treatment of metabolic disorders in the heart." (PMID 37667357, 2023). "Collectively, our results demonstrate that Plin5 is highly related to the coordination of fatty acid and glucose oxidation in cardiomyocytes, providing a potential target for the treatment of metabolic disorders in the heart." (PMID 37667357, 2023). "Other studies have revealed that Plin5 can reduce FFA-induced metabolic disorders and inflammation, mainly because Plin5 relies on sirtuin 1 to promote autophagy." (PMID 34638947, 2021). "The aim of this review is to dissect the recent findings and functions of PLIN5 in lipid metabolism, metabolic disorders, and NAFLD as well as the progression of NAFLD to HCC." (PMID 34067931, 2021). "Plin5 regulates cardiac energy metabolism by balancing the oxidation of two key metabolic substrates, fatty acids, and glucose, thereby ameliorating cardiac energy metabolic disorders." (PMID 40166465, 2025).
cardiovascular diseases (3 papers, 2019 to 2022). "As a lipid droplet (LD) decomposition barrier, Plin5 can protect LDs from lipase decomposition and regulate lipid metabolism, which is involved in the occurrence and development of cardiovascular diseases." (PMID 35509833, 2022). "On the other hand, adrenaline, secreted by sympathetic excitability in the case of cold, tension, fear, and so on, is able to activate PKA and increase the phosphorylation of Plin5, which may prompt the incidence of cardiovascular disease, especially in T2DM patients." (PMID 31772713, 2019).
heart disease (1 paper, 2023). "The protection from lipotoxic heart disease in Plin5-Tg mice prompted us to study heart function and energy metabolism under HFD-induced metabolic stress." (PMID 37150323, 2023).
kidney disease (1 paper, 2023). "Healthy controls and kidney disease samples showed strong expression of DNL genes, including ACSS2, NR1H3 (liver X receptor α [LXRA]), NR1H4 (farnesoid X receptor [FXR]), SREBF1, SCAP, PLIN2, PLIN5, ACACAB, ATP citrate lyase (ACLY), and FASN in PT cells and some other tubule cells." (PMID 38051585, 2023).
PLIN5 also shares sentences with these, for which no sentence is quoted: pancreatic cancer (2 papers); rhabdomyosarcoma (2); atrial fibrillation (1); dermatofibrosarcoma protuberans (1); Ewing sarcoma (1); fibrosarcoma (1); gastric cancer (1); Hyperinsulinemia (1); hypertriglyceridemia (1); hypertrophy (1); inflammatory bowel disease (1); lentivirus infection (1); lung adenocarcinoma (1); lung carcinoma (1); lymph node metastasis (1); Parkinson disease (1); undifferentiated sarcomas (1); vascular disorder (1).